RNF43 (ring finger protein 43)
Diseases named in the same sentence as RNF43 in open-access papers (continued):
Sharing a sentence is not in itself a finding about the gene and the disease.
colorectal cancer (continued). "Second, clinico-pathological features suggested many of the APC-mutated CACs were actually sporadic colorectal cancer whereas RNF43-mutated CACs did not have this tendency." (PMID 29416670, 2018). "Functionally, it was shown that RNF43 as well as ZNRF3 mutant colorectal cancers may be Wnt ligand dependent and that inhibition of the Wnt signal by targeting Porcupine may facilitate decreased growth of a proportion of MSI serrated pathway cancers." (PMID 27661107, 2016). "The significance of this finding is not clear since RNF43 mutations and APC mutations in colorectal cancer are mutually exclusive and the localization of RNF43 on the inner layer of the nuclear membrane has not been demonstrated." (PMID 27338477, 2016). "While secreted membrane bound RNF43 protein gene was known to be up-regulated in colorectal cancer." (PMID 23282184, 2012). "While RNF43 and RNF183 have been previously implicated in colorectal cancer progression, the consistent and significant elevation of RNF39, a comparatively understudied member of this protein family, suggests it may function as a novel and distinct regulator in COAD pathogenesis." (PMID 41457280, 2026). "Our data suggests a predictive role for RNF43 mutation in response to encorafenib and cetuximab and when viewed in the context of other available data, suggests the utility of routine testing of RNF43 in patients with BRAF-mutated colorectal cancer, if external validation is supportive." (PMID 41002577, 2025). "Moreover, the recent advances in molecular techniques, in particular Next-Generation Sequencing, have led to the identification of many new genes involved in the predisposition to colorectal cancers, such as RPS20, POLE, POLD1, AXIN2, NTHL1, MSH3, RNF43 and GREM1." (PMID 36768460, 2023). "Loss‐of‐function mutations in RNF43 induce activation of Wnt ligand‐dependent Wnt/β‐catenin signaling through stabilization of the Frizzled receptor, which is often found in microsatellite instability (MSI)‐type colorectal cancer (CRC) that develops from sessile serrated adenomas." (PMID 35040131, 2022). "Importantly, Kaplan–Meier analysis revealed that co-occurrence of RNF43 and KRAS mutations was associated with a poorer outcome for colorectal cancer, compared to single mutations of each gene, although the samples size was not enough to obtain significant differences." (PMID 32934222, 2020). "Homeobox C6 overexpression reduces the RNF43 and AXIN2 expression levels, leading to a poor prognosis for patients with colorectal cancer." (PMID 41487817, 2025). "The RNF43-, CYP2S1- and LIF-related super-enhancers are shown as colorectal cancer–specific super-enhancers since the odds ratio of these three gene-related super-enhancers are >20 (P < 0.05) in primary tissues and >15 in cell lines (P < 0.05)." (PMID 37207350, 2023). "A clinical trial of the peptide vaccines RNF43 and TOMM34 combined with chemotherapy for stage III colorectal cancer revealed that patients with a positive CTL response showed good 3-year relapse-free survival regardless of HLA-A*2402 status." (PMID 36845719, 2023). "RNF43 and ZNRF3 are regarded as tumor suppressors in multiple cancer types, such as gastric, ovarian, pancreatic, endometrial, and colorectal cancers." (PMID 35204808, 2022). "This highlights the importance of the Hippo/YAP pathway in RNF43-mutant pancreatic cancer and is consistent with the observation of YAP dependency in APC/CTNNB1-mutant colorectal cancers." (PMID 35536676, 2022). "Among these, a chimeric transcript resulting from the fusion of RNF43 and SUPT4H1 was found to occur frequently in primary colorectal carcinoma." (PMID 27461012, 2016). "Several TAAs expressed by colorectal cancer cells—such as carcino-embryonic antigen (CEA), MUC-1, survivin, beta-human chorionic gonadotropin (hCG) and ring finger protein 43 (RNF43)—have been targeted via peptide vaccines." (PMID 26510455, 2015).
colorectal cancer (continued). "RING finger protein 43 (RNF43), an E3-type ubiquitin ligase, is frequently up-regulated in human colorectal cancer." (PMID 24466159, 2014). "Three-fourths of colorectal cancers possessed APC alterations and about one in four of these cases possessed also concomitant alterations in other genes of the WNT/β-catenin/APC pathway, including RNF43, CTNNB1, and TCF7L2." (PMID 40061138, 2025). "Colorectal cancers with alterations in RNF43, CTNNB1, and TCF7L2 without APC alterations presented more commonly MSI and a high TMB." (PMID 40061138, 2025). "The mutual exclusivity of RNF43 and APC mutations observed in the current report was previously reported in colorectal cancer in a report that did not examine CDX2 suppression." (PMID 39452477, 2024). "Additionally, the POP112 line did not harbour mutations or deep amplifications or deletions in the WNT pathway members defined as colorectal cancer drivers APC, AXIN1, AXIN2, CTNNB1, GSK3B or RNF43, and only a shallow deletion in ZNRF3." (PMID 38324534, 2024). "Although loss of function mutations in RNF43 are currently not directly targetable, they have been associated with the response to anti-EGFR/BRAF combination therapies in microsatellite-stable BRAF-mutated colorectal cancers." (PMID 39452477, 2024). "It was discovered that colorectal cancers possessed significant differences in their genomic profile dependent on whether the WNT/β-catenin/APC pathway was activated through alterations in APC or through alterations in three alternative genes of the pathway, RNF43, CTNNB1, and TCF7L2." (PMID 40061138, 2025). "Our work began with computational studies of public data identifying a strong negative correlation between ZNRF3/RNF43 mRNA levels and EGFR protein expression in datasets of human adrenocortical carcinomas and colorectal cancers." (PMID 38260423, 2024). "Furthermore, we validated ZNRF3/RNF43-EGFR signaling in prostate cancer, one of the several other tumors in patients besides colorectal cancer that showed a negative correlation ZNRF3/RNF43 mRNA and EGFR protein levels." (PMID 38260423, 2024).
pancreatic cancer (46 papers, 2016 to 2025). "Compound 11 was moreover capable of reducing the viability of a specific group of RNF43-mutated pancreatic cancer cells (e.g., HPAF-II), whose survival is dependent on functional WNT signaling." (PMID 40992662, 2025). "RNF43 is frequently mutated in ovarian, colon, and pancreatic cancers and functions as a tumor suppressor." (PMID 40608411, 2025). "Here, it is found that RNF43‐mutated pancreatic cancer cells exhibit elevated B‐RAF/MEK activity and are highly sensitive to MEK inhibitors." (PMID 38225722, 2024). "MEK and WNT inhibitors synergistically suppress the growth of RNF43‐mutated pancreatic cancer cells in vitro and in vivo." (PMID 38225722, 2024). "Consistent with the results for pancreatic cancer, RNF43‐mutated SW48 colon cancer cells were more sensitive to the three MEK inhibitors than CaCO2 cells expressing wild‐type RNF43." (PMID 38225722, 2024). "RNF43 is frequently mutated in mucinous ovarian and pancreatic carcinomas, and mucinous differentiation is often found in serrated colorectal carcinomas, to which germline RNF43 variants are thought to predispose." (PMID 38725616, 2024). "PORCN inhibitor–resistant RNF43-mutant pancreatic cancer cell lines harbor loss-of-function genetic alterations in EP300." (PMID 35536676, 2022). "WNT secretion is also targeted by some inhibitors like the inhibitor IWP-2 for treatment of cancers, especially pancreatic cancers with RNF43 mutations, whereas PORCN inhibitors WNT974 and ETC-159 are applicable to prevent mammary tumors and cancer stem cells." (PMID 35965500, 2022). "Somatic mutations in RNF43 occur 9%–10% of colorectal (∼4% in microsatellite stable disease) and approximately 7% of pancreatic cancers." (PMID 36922934, 2022). "RNF43 mutations are the most common Wnt pathway mutations in pancreatic cancer, observed in 5-10% of cases." (PMID 35358569, 2022). "Taken together, these results indicate that downregulation of GATA6 mediated the PORCN inhibitor resistance caused by p300 loss in RNF43-mutant pancreatic cancers." (PMID 35536676, 2022). "Previous studies have suggested that Porcupine inhibitors, including LGK974 and IWP-2, significantly inhibit the proliferation of pancreatic cancer cell lines and the tumor growth of patient-derived xenografts with inactivating RNF43 mutations." (PMID 35487932, 2022). "While genetic alterations in EP300 occur in less than 2% of treatment-naive pancreatic tumors, cooccurrence of EP300 and RNF43 mutations has been observed in resected pancreatic tumors." (PMID 35536676, 2022). "FZD5 mainly expressed in RNF43 mutated tumor cells was proposed as a molecular target for pancreatic cancer treatment." (PMID 33291655, 2020). "RNF43 mutations are found in 5–10% of pancreatic cancers, while RPSO3 translocations are found in 10% of colorectal cancers." (PMID 33092630, 2020). "The HPAF-II pancreatic cancer cells contain a RNF43 missense mutation that makes them addicted to Wnt signaling." (PMID 33092630, 2020). "In pancreatic cancer, RNF43 mutations located within or upstream the RING domain were identified and cell lines with such mutations were shown to be sensitive to inhibitors of Wnt ligand secretion." (PMID 31811196, 2019). "Currently there is a phase I clinical trial on-going evaluating WNT inhibitors in patients with malignancies dependent on WNT ligands and includes patients with RNF43-mutated pancreatic cancer." (PMID 29329208, 2018). "The porcupine inhibitor LGK974 has been shown to dramatically reduce growth of pancreatic cancer cells that carry an RNF43 mutation." (PMID 27661107, 2016). "It should be noted that RNF43 mutant tumors depend on the Wnt pathway even in the presence of KRAS mutations that are nearly universal in pancreatic cancer." (PMID 27338477, 2016). "In addition, the results of a recent in vitro study reported that RNF43-mutated pancreatic cancer cells show elevated B-RAF/MEK activity and are highly sensitive to MEK inhibitors." (PMID 40735046, 2025).
pancreatic cancer (continued). "Interestingly, RNF43 mutations in pancreatic cancer shift the pancreatic cancer dependency to WNT signaling rather than oncogenic KRAS, further underscoring the importance of this E3 ligase as a negative regulator of WNT signaling and a tumor suppressor." (PMID 39851497, 2025). "RNF43‐mutated pancreatic cancer cells exhibited enhanced MEK activity." (PMID 38225722, 2024). "RNF43 is mutated in various solid tumors, including pancreatic cancer." (PMID 38225722, 2024). "Besides, RNF43 is frequently mutated in colorectal, endometrial cancers, and pancreatic cancer, which can deeply affect the behavior of cancer cells and induce cancerogenesis and progression." (PMID 37848933, 2023). "Studies of the precursors of pancreatic cancer have identified RNF43 mutations in both neoplastic cysts of the pancreas and pancreatic intraepithelial neoplasia (PanIN), and recent advances in genome sequencing have identified loss-of-function RNF43 mutations in 5%–10% of pancreatic cancers." (PMID 35536676, 2022). "We speculated that there is a general Wnt dependency in the classical subtype of pancreatic cancer, a subset of which are hyper–Wnt addicted due to RNF43 mutations." (PMID 35536676, 2022). "Interestingly, RNF43 has a negative regulatory action on the Wnt signaling, which is closely related to the underlying mechanism of pancreatic cancer with metastases." (PMID 34178672, 2021). "In addition, proliferation of RNF43-mutated pancreatic cancers is suppressed by the re-expression of wild-type RNF43." (PMID 27338477, 2016). "The cholangiocarcinoma cell line EGI‐1 (Wnt‐addicted due to an R‐spondin translocation), the ovarian cancer cell line MCAS (Wnt‐addicted due to an RNF43 mutation), and the pancreatic cancer cell line CFPAC‐1 (sensitive to Wnt inhibition, mechanism unknown) were used." (PMID 33660437, 2021). "With the broader adoption of next generation sequencing, mutations of RNF43 were subsequently identified in a variety of cancers including colorectal adenocarcinomas, endometrial carcinomas, mucinous ovarian carcinoma, pancreatic cancer, and gastric cancer at frequencies ranging from 4.0% to 18.9%." (PMID 27338477, 2016). "These included AsPC-1 pancreatic cancer orthotopic xenografts and pancreatic cancer patient-derived xenograft (PDX) PAXF1861, both with loss-of-function RNF43 mutations, and a colorectal PDX with an R-spondin translocation." (PMID 38488003, 2024). "In line with the previous screen, Cdkn2a was the top-scoring gene followed by Rnf43 and the newly identified genes, Usp15 and Scaf1, further supporting their function as strong suppressors of pancreatic cancer in KC mice." (PMID 38902237, 2024). "RING finger 43 (RNF43), a RING‐type E3 ubiquitin ligase, is a key regulator of WNT signaling and is mutated in 6–10% of pancreatic tumors." (PMID 38225722, 2024). "For instance, WNT974 treatment inhibited the growth of RNF43-mutant pancreatic tumours in a xenograft model." (PMID 37048063, 2023). "These genetically engineered mouse model (GEMM) data, plus the high prevalence of ARID1A/RNF43 mutations in our cohort and other PDAC cohorts, established that these two genes were bona fide tumor suppressor genes for pancreatic cancer." (PMID 36999792, 2023). "Treatment of an RNF43-mutant pancreatic cancer cell line with a PORCNi led to a pronounced decrease in the expression of ribosomal protein genes and ribosome biogenesis genes." (PMID 37048063, 2023). "Furthermore, RNF43 mutational status is an indicator of sensitivity to Wnt pathway inhibitors and these mutations may thus be useful in predicting therapeutic response for pancreatic cancers which may arise from IPMN precursor lesions." (PMID 36454217, 2023). "Consistent with this, the Sato and Clevers labs reported that the GATA6-high classical subtype tumor cells from RNF43-WT pancreatic cancers rely on Wnts to grow as organoids ex vivo." (PMID 35536676, 2022).
pancreatic cancer (continued). "Examples include patients with colorectal or pancreatic cancer with RSPO2/3 fusions and LoF RNF43 mutations." (PMID 36922934, 2022). "In vivo CRISPR screens identified essential genes and tumor suppressors in RNF43-mutant pancreatic cancer." (PMID 35536676, 2022). "However, a significant proportion of organoids derived from PDAC patients with wild-type RNF43 also remained dependent on Wnt ligands, suggesting opportunities for Porcupine inhibitors and other ligand-dependent therapeutics exist beyond RNF43 mutations in pancreatic cancers." (PMID 35358569, 2022). "Previous studies have shown that Wnt deprivation induces differentiation of RNF43-mutant pancreatic tumors." (PMID 35536676, 2022). "Last but not least, our findings provide a rationale for using p300 and GATA6 expression status to further stratify patient selection in RNF43-mutant pancreatic cancers to maximize the clinical efficacy of Wnt inhibitors." (PMID 35536676, 2022). "Although RNF43 is the 3rd most frequently mutated gene in pancreatic tumor tissues of IPMN patients, the causative relationship between loss of RNF43 and IPMN is yet to be established." (PMID 35229994, 2022). "This is similar to the tumor differentiation observed in other PORCN inhibitor–sensitive RNF43-mutant pancreatic tumors following Wnt inhibition." (PMID 35536676, 2022). "These RNF43-mutant pancreatic tumors are therefore hypersensitive to and dependent on ligand-activated Wnt signaling and can be pharmacologically targeted by upstream Wnt pathway inhibition." (PMID 35536676, 2022). "We found that EP300 is silenced due to genetic alterations in all the existing RNF43-mutant pancreatic cancer cell lines that are resistant to PORCN inhibitors." (PMID 35536676, 2022). "This pattern was also seen when we compared the existing RNF43/EP300-mutant pancreatic cancer cell lines with the EP300-WT cell lines." (PMID 35536676, 2022). "Supporting its importance, we found that EP300 is inactivated in the preexisting PORCN inhibitor–resistant RNF43-mutant pancreatic cancer cell lines." (PMID 35536676, 2022). "Our previous study showed that a relatively small scale CRISPR library can be faithfully represented in subcutaneous xenografts of HPAF-II cells, a PORCN inhibitor–sensitive RNF43-mutant pancreatic cancer model." (PMID 35536676, 2022). "Here, we examined why some RNF43-mutant pancreatic tumors are insensitive to Wnt pathway inhibition, using a potent drug currently in clinical trials." (PMID 35536676, 2022). "To elucidate potential mechanisms, we performed in vivo CRISPR screens in PORCN inhibitor–sensitive RNF43-mutant pancreatic cancer xenografts." (PMID 35536676, 2022). "Mutant RNF43 almost exclusively occurs along with abnormal KRAS and therefore, KRAS mutation is likely required for RNF43 mutation‐associated pancreatic cancer development." (PMID 35229994, 2022). "This identifies a more general role for a p300/GATA6 axis in cancer and suggests that p300 and GATA6 status can be used to stratify RNF43-mutant pancreatic cancer patients to maximize the clinical benefits of PORCN inhibitors." (PMID 35536676, 2022). "RNF43-mutant pancreatic cancers are dependent on Wnt production, and pharmacologic blockade of the pathway, e.g., by PORCN inhibitors, leads to tumor differentiation." (PMID 35536676, 2022). "For example, in a library of patient-derived pancreatic tumor organoids, one RNF43-mutant organoid line, PC43, grew independently of Wnt signaling." (PMID 35536676, 2022). "GDSC analysis showed that mTOR inhibitors are very sensitive to pancreatic cancer cells with mutations in EWSR1.FLI1 and RNF43." (PMID 34461940, 2021).